MIR34A (microRNA 34a)
Synonyms: hsa-mir-34a; MIRN34A; miRNA34A; mir-34; mir-34a
Gene: MicroRNA gene on chromosome 1 (9,151,668 to 9,151,777, reverse strand). Ensembl gene ENSG00000284357.
Gene Ontology:
Biological process: miRNA-mediated post-transcriptional gene silencing
Homologues: Orthologues: chimpanzee ptr-mir-34a (100% identical), macaque mml-mir-34a (97% identical), guinea pig MIR34A (72% identical), rat Mir34a (72% identical), mouse Mir34a (71% identical), tropical clawed frog xtr-mir-34a (65% identical), zebrafish mir34a (64% identical), dog MIR34A (56% identical), Caenorhabditis elegans cel-mir-34 (36% identical), Drosophila melanogaster mir-34 (35% identical). Paralogues in human: MIR34B (39% identical), MIR34C (32% identical).
Diseases named in the same sentence as MIR34A in open-access papers:
MIR34A is named in the same sentence as 30 diseases in open-access papers, as found by Europe PMC text mining. Sharing a sentence is not in itself a finding about the gene and the disease. The quoted sentences say what the papers report.
colon cancer (5 papers, 2022 to 2026). "We had previously reported that germline deletion of Mir34a enhances tumor initiation, progression and invasion in a murine model of colitis-associated colon cancer." (PMID 39425000, 2025). "We had previously observed that germline deletion of Mir34a enhances tumor initiation, progression, and invasion in a murine model of colitis-associated colon cancer." (PMID 39425000, 2025). "Here we determined whether myeloid Mir34a has a tumor suppressive function in ApcMin/+ mice, a model for intestinal and colon cancer." (PMID 42140945, 2026). "In this study, the phytochemicals of TY increased the expression level of MIR34a, which may be associated with demethylation of the promoter region of MIR34a because the promoter of MIR34a is frequently hypermethylated in colon cancer cells." (PMID 35428370, 2022).
colorectal cancer (3 papers, 2020 to 2025). A primary or metastatic malignant neoplasm that affects the colon or rectum. "Furthermore, in colorectal cancer Mir34a was shown to constrain carcinogenesis by directly inhibiting an IL-6R/STAT3/Mir34a feedback loop, and its ablation is required to induce IL6-mediated EMT and invasion." (PMID 32541781, 2020). "In turn, the CN regions contained three known microRNAs (MIR34A, MIR367 and MIR302A) that regulate the expression of genes involved in the pathogenesis of colorectal cancer." (PMID 34202891, 2021).
adenoma (2 papers, 2020 to 2022). A neoplasm arising from the epithelium. "In tumoroids derived from Csf1r-deficient and Csf1r/Mir34a-deficient adenomas, moderate transcriptome changes with lower numbers of differentially regulated genes were observed." (PMID 36147476, 2022). "The expression of Csf1r was up-regulated in Mir34a-deficient adenomas and pri-Mir34a expression was increased in Csf1r-deficient adenomas on the mRNA and protein levels." (PMID 36147476, 2022). "Six predicted Mir34a targets (Arhgap44, Ccnjl, Clec16a, Esyt3, Golga7b, Grap) were up-regulated in both Mir34a-deficient adenomas and tumoroids." (PMID 36147476, 2022). "Remarkably, the up-regulation of predicted Mir34a targets in Mir34a-deficient adenomas was largely abrogated by co-deletion of Csf1r." (PMID 36147476, 2022). "In Mir34a-deficient adenomas, we identified a set of 62 significantly up-regulated mRNAs with Mir34a seed-matching sites in their 3'-UTR." (PMID 36147476, 2022). "Differential gene expression analyses using DESeq2 showed that in adenomas from Mir34a-deficient mice, 301 genes were significantly up- and 127 genes were down-regulated when compared to adenomas from control mice." (PMID 36147476, 2022). "Taken together, deletion of Csf1r largely reversed the effects of Mir34a loss on infiltration by fibroblasts, immune cells and bacteria in adenomas." (PMID 36147476, 2022). "The size of adenomas was significantly larger in Mir34a-deficient and smaller in Csf1r-deficient ApcMin/+ mice when compared to Csf1rfl/fl;Mir34afl/fl;ApcMin/+ mice." (PMID 36147476, 2022). "Next, we analyzed which Mir34a targets were significantly up-regulated in either Mir34a-deficient adenomas and/or tumoroids." (PMID 36147476, 2022). "Remarkably, the up-regulation of factors involved in EMT, stemness, Wnt signaling and extracellular matrix components in Mir34a-deficient adenomas and/or tumoroids was largely abrogated by co-deletion of Csf1r." (PMID 36147476, 2022). "On the contrary, proliferation was increased and apoptosis was decreased in Mir34a-deficient adenomas." (PMID 36147476, 2022). "Tumor-associated fibroblasts were increased within adenomas in Mir34a-deficient adenomas, whereas deletion of Csf1r resulted in their decrease." (PMID 36147476, 2022). "RNA-Seq results were confirmed by qPCR analysis of selected RNAs up-regulated in Mir34a-deficient adenomas and/or tumoroids." (PMID 36147476, 2022). "Indeed, tumoroids derived from Mir34a-deficient adenomas displayed an increase in formation rate and mean size, whereas tumoroids derived from Csf1r-deficient adenomas formed at a decreased rate and were smaller." (PMID 36147476, 2022). "Therefore, the enhanced frequency of stem cells observed in Mir34a-deficient adenomas and normal intestinal crypts, was dependent on the increased expression of Csf1r." (PMID 36147476, 2022). "Furthermore, loss of Mir34a in adenomas was associated with the induction of RNAs commonly up-regulated after IL6 treatment, which includes STAT3 activation." (PMID 36147476, 2022). "In Mir34a-deficient adenomas, EMT-associated genes were strongly up-regulated." (PMID 36147476, 2022). "Indeed, GSEA showed that loss of Mir34a in adenomas, and to a lesser extent in tumoroids, was associated with the induction of STAT3, JUN and SRF expression signatures." (PMID 36147476, 2022). "Interestingly, Lgr5, which was up-regulated in Mir34a-deficient adenomas and down-regulated in Csf1r-deficient adenomas, is not only a stem cell marker, but also potentiates Wnt/β-catenin signaling." (PMID 36147476, 2022). "Furthermore, FISH with the universal eubacteria-specific probe (EUB338) revealed that Mir34a-deficient adenomas displayed more bacterial infiltration, whereas less bacterial infiltration was observed in Csf1r-deficient adenomas." (PMID 36147476, 2022).
adenoma (continued). "In addition, we performed NGS analyses of tumoroids derived from Mir34a- and/or Csf1r-deficient adenomas in order to identify cell autonomous changes in gene expression, which are not potentially confounded by interactions of tumor cells with the tumor-microenvironment, as in the adenomas." (PMID 36147476, 2022). "Therefore, we analyzed whether expression signatures comprising RNAs commonly up-regulated after induction of these TFs were associated with loss of Mir34a in adenomas and/or tumoroids." (PMID 36147476, 2022). "Therefore, Csf1r is required for the recruitment of fibroblasts in Mir34a-deficient adenomas." (PMID 36147476, 2022). "However, in adenomas from Csf1r/Mir34a-deficient mice ApcMin/+ mice only 15 genes were significantly up- and 17 genes were down-regulated, indicating that the gene expression changes observed in Mir34a-deficient adenomas were largely abrogated by the concomitant deletion of Csf1r." (PMID 36147476, 2022). "Here, ApcMin/+ mice with intestinal-epithelial cell (IEC)-specific deletions of Mir34a showed increased formation of adenomas and decreased survival, whereas deletion of Csf1r decreased adenoma formation and increased survival." (PMID 36147476, 2022). "Next we used Gene Set Enrichment Analyses (GSEA) to identify pathways that are differentially regulated in adenomas and tumoroids dependent on their Mir34a and Csf1r status." (PMID 36147476, 2022). "In order to obtain functional evidence for Mir34a/Csf1r mediated regulation of stemness in adenomas, we performed a tumoroid formation assay." (PMID 36147476, 2022). "In adenomas deletion of Mir34a enhanced proliferation, STAT3 signaling, infiltration with fibroblasts, immune cells and microbes, and tumor stem cell abundance and decreased apoptosis." (PMID 36147476, 2022). "However, the divergent effects of Mir34a-deficiency in adenomas and in tumoroids may in part be due to interactions between Mir34a-deficient tumor cells in the adenomas and cells within the tumor microenvironment, such as infiltrating macrophages, which do not occur in tumoroids." (PMID 36147476, 2022). "mRNAs containing Mir34a seed-matching sites, which encode proteins related to EMT (epithelial-mesenchymal transition), stemness and Wnt signaling, were enriched after Mir34a inactivation in adenomas and derived tumoroids." (PMID 36147476, 2022). "Notably, concomitant Mir34a and Csf1r deletion resulted in unchanged numbers of fibroblasts within adenomas." (PMID 36147476, 2022). "Consistent with the finding that activation of CSF1R induces STAT3 phosphorylation (p-STAT3) in CRC cell lines 21, the frequency of cells displaying STAT3 activation was decreased in adenomas of Csf1rΔIEC;ApcMin/+ mice, whereas deletion of Mir34a increased the number of p-STAT3-positive tumor cells." (PMID 36147476, 2022). "An example of those signatures is the MIR34A gene expression, which plays a critical role in all stages of colorectal carcinogenesis, starting from colon epithelium proliferation, dysplasia, early/late adenoma, and progression to malignant neoplasm." (PMID 33037254, 2020).
atherosclerosis (2 papers, 2021 to 2023). A disease characterized by the build-up of fatty material and calcium deposition in the arterial wall resulting in partial or complete occlusion of the arterial lumen. "Additionally, MIR34A is abnormally expressed in some age-related diseases, such as age-associated heart failure, atherosclerosis, and posterior capsule opacification." (PMID 37414399, 2023). "Since global or macrophages-selective Mir34a ablation affects atherosclerosis to a similar extent, the authors suggest that macrophages-specific expression of miR-34a may have a more crushing effect in the pathology onset compared to hepatic miR-34a." (PMID 34698884, 2021).
hepatocellular carcinoma (2 papers, 2020 to 2023). A malignant tumor that arises from hepatocytes. "Previous studies have shown that MIR34A is involved in various diseases, including myocardial infarction, senescence, tuberous sclerosis complex, and hepatocellular carcinoma." (PMID 37414399, 2023).
intestinal tumors (2 papers, 2022 to 2026). "Intestinal tumors in myeloid Mir34a-deficient mice showed elevated expression of several known Mir34a target mRNAs, including Csf1r, Pd-l1, Mmp9, Ccl22, and c-Myc." (PMID 42140945, 2026). "When the entire small intestinal tract from 18 weeks old ApcMin/+ mice was examined, Csf1r-deficient ApcMin/+ mice showed a significantly reduced number of intestinal tumors, whereas Mir34a-deficient mice showed a dramatic increase in tumor numbers." (PMID 36147476, 2022). "In addition, the number of immuno-suppressive, pro-tumorigenic CD4+Foxp3+ Treg cells increased in myeloid Mir34a-deficient intestinal tumors." (PMID 42140945, 2026). "Taken together, the effects of the single deletions of Mir34a and Csf1r were neutralized by simultaneous inactivation of both genes, implying that Mir34a and Csf1r functionally antagonize each other during intestinal tumor formation and progression." (PMID 36147476, 2022). "In order to determine, whether inactivation of Mir34a affects intestinal tumor formation in a Csf1r-dependent manner, we generated ApcMin/+ mice with inactivation of Mir34a, Csf1r or of both genes in IECs." (PMID 36147476, 2022). "Notably, ApcMin/+ mice with deletion of both Mir34a and Csf1r displayed similar frequencies of intestinal tumors as Csf1rfl/fl;Mir34afl/fl;ApcMin/+ mice." (PMID 36147476, 2022).
neuroblastoma (2 papers, 2015 to 2017). Neuroblastoma (NB) is the most common solid, extracranial childhood tumor. "Although it was demonstrated that Myc binds to the MIR34A promoter, further studies suggested that epigenetic silencing or chromosomal deletion of the MIR34A genomic locus could be responsible for miR-34a downregulation in neuroblastoma as well." (PMID 29022903, 2017).
cataract (1 paper, 2023). Partial or complete opacity of the crystalline lens of one or both eyes that decreases visual acuity and eventually results in blindness. "Consistent with a previous study, our results showed overexpression of MIR34A in the LECs of cataracts." (PMID 37414399, 2023). "Based on this finding, we focused on the function of MIR34A and HK1 in the progress of cataracts, whereby the human lens epithelial cell line SRA01/04 and mouse lens were treated with MIR34A mimics and HK1 siRNA." (PMID 37414399, 2023). "Specifically, our results from cultured cells and mouse lenses reveal that MIR34A modulates the HK1/caspase 3 signaling pathway and has a crucial role in LEC apoptosis and cataracts." (PMID 37414399, 2023). "Many questions remain to be answered in mice, including whether the expression of HK1 is abnormal in the LECs of mice and whether regulating the expression of MIR34A and HK1 can prevent cataracts." (PMID 37414399, 2023). "Therefore, to determine whether MIR34A modulates LEC apoptosis and cataracts through the HK1/caspase 3 signaling pathway, we detected the expression of caspase 3 with or without MIR34A mimics or siHK1." (PMID 37414399, 2023). "To evaluate whether Mir34a plays a crucial role in the pathological development of cataracts via regulating the expression of HK1, we cultured the mouse lens in vitro with or without Mir34a mimics, siHk1, or Hk1 inhibitor (deoxyglucose)." (PMID 37414399, 2023).
intestinal cancer (1 paper, 2022). "Apart from the opposing effects of Mir34a and Csf1r on proliferation, apoptosis and STAT3 signaling, their antagonistic effects on the tumor-environment and intestinal cancer stem cells might also be responsible for the compensatory effect of deleting both genes." (PMID 36147476, 2022).
pancreatic cancer (1 paper, 2020). "To study the role of Mir34a in pancreatic cancer development we crossed the Mir34afl/fl mice with the well described Kras mouse model for PDAC38 to generate Ptf1a+/Cre; Kras+/LSL-G12D; Mir34afl/fl mice (hereafter called: KrasG12D; Mir34aΔ/Δ), which were analysed at specific time points." (PMID 32541781, 2020).
papillary thyroid cancer (1 paper, 2019). "In addition, MIR34A can down-regulate GAS1 expression level and its overexpression could promote cancer cell proliferation, stimulate colony formation and suppress cell apoptosis in late-stage papillary thyroid cancer." (PMID 31126066, 2019).
prostate carcinoma (1 paper, 2022). A carcinoma that arises from epithelial cells of the prostate gland. "Further investigation revealed the relationship between autophagy and MIR34A cell death in prostate cancer cells." (PMID 35317831, 2022). "MIR34A is a tumor-suppressor factor in prostate cancer and mediating its delivery by chitosan nanoparticles promotes its potential in cancer suppression." (PMID 35317831, 2022). "MIR34A-loaded chitosan nanoparticles stimulate autophagy in prostate cancer cells independent of BECN1, ATG4, ATG5 and ATG7, known as non-canonical autophagy." (PMID 35317831, 2022). "Autophagy induction by MIR34A negatively affects survival of prostate cancer cells, so that apoptosis inhibition does not block the anti-proliferative activity of MIR34A-mediatd autophagy." (PMID 35317831, 2022).
thyroid cancer (1 paper, 2019). "The mutated TF MZF1 could negatively regulate target gene GAS1, which was also suppressed by MIR34A, to cause the proliferation and suppress the apoptosis of thyroid cancer cells." (PMID 31126066, 2019).
tumor (12 papers, 2015 to 2026). "Among the M2-like macrophage-derived factors with a known role in tumor progression, Pdgfc and Il10 were upregulated in Mir34a-deficient macrophages, particularly in the Mrc1+ subtype." (PMID 39425000, 2025). "Here, Mir34a inactivation resulted in a Csf1r-dependent increase in tumor-associated fibroblasts, macrophages, neutrophils, T- and B-cells." (PMID 36147476, 2022). "Loss of Mir34a facilitated the polarization of tumor-associated macrophages (TAMs) towards a pro-tumorigenic M2-like state, implying that Mir34a is required to maintain TAMs in a tumor-suppressive state." (PMID 42140945, 2026). "Taken together, these results imply that the elevated expression of Csf1r caused by Mir34a-deficiency may play a major role in tumor progression via TME—tumor cell interactions in the mouse model analyzed here." (PMID 39425000, 2025). "Therefore, Csf1r is a required mediator of the effects of Mir34a inactivation in tumor-associated myeloid cells." (PMID 39425000, 2025). "Therefore, the up-regulation of Csf1r presumably mediated the effects of Mir34a loss on the tumor microenvironment." (PMID 36147476, 2022). "In addition, these results partially agree with the observations obtained by genetic inactivation of Csf1r in Mir34a-deficient myeloid cells and further confirm Csf1r-inhibition as an important mediator of non-tumor-cell autonomous suppression of CACs by miR-34a." (PMID 39425000, 2025). "However, it remained unknown whether the effects of the Mir34a inactivation were tumor cell autonomous, or whether Mir34a-deficient cells within the tumor stroma were also involved." (PMID 39425000, 2025). "Myeloid cell-specific deletion of Mir34a in ApcMin/+ mice increased tumor initiation and allowed progression towards invasive carcinomas, which are generally not observed in ApcMin/+ mice." (PMID 42140945, 2026). "Taken together, these results suggested a tumor suppressive role of Mir34a in both, the intestinal epithelial cells and in TAMs." (PMID 39425000, 2025). "Surprisingly, tumor invasiveness was increased to a larger extent by inactivation of Mir34a in myeloid cells than by its deletion in intestinal epithelial cells." (PMID 39425000, 2025). "Here, we determined a tumor suppressive role for Mir34a, whereas Csf1r displayed a tumor-promoting function in intestinal epithelial cells." (PMID 36147476, 2022). "Our findings provide genetic proof of an important role of Csf1r down-regulation for tumor suppression by Mir34a during intestinal tumorigenesis." (PMID 36147476, 2022). "At least five genes located at 1p36 (CHD5, CAMTA1, KIF1B, CASZ1, and MIR34A) were already suggested to be tumor suppressors." (PMID 34956867, 2021). "Overall, our results suggest that apart from its known tumor suppressor role, Mir34a also has an anti-inflammatory role in the pancreas by downregulating TNFA and IL6." (PMID 32541781, 2020). "Here, we present an in vivo study of the tumour suppressive role of Mir34a in PDAC using genetically engineered mouse models." (PMID 32541781, 2020). "The tumor load of Mir34aΔIEC and Mir34aΔMye mice was less than in Mir34a–/– mice." (PMID 39425000, 2025). "However, to achieve a better understanding of the crosstalk between myeloid Mir34a-deficient stromal cells and CAC cells and to identify myeloid cell-secreted factors that promote tumor progression, further investigations are needed." (PMID 39425000, 2025).